RASL11B (RAS like family 11 member B)
Tractability: No criterion of Open Targets' tractability assessment is met for any kind of drug.
Gene: Protein-coding gene on chromosome 4 (52,862,317 to 52,866,835, forward strand). Ensembl gene ENSG00000128045.
Subcellular location (Human Protein Atlas): Nuclear bodies
Gene Ontology:
Molecular function: protein binding; GTPase activity; G protein activity; GTP binding; transforming growth factor beta receptor binding
Genetic constraint (gnomAD): Loss-of-function variants: 11 observed, 18.62 expected, observed/expected ratio (o/e) 0.59, 90% interval 0.37 to 0.98. The upper end of that interval is the gene's LOEUF score, 0.98, which puts it in group 4 of 6, group 1 being the genes least tolerant of losing a copy. Missense variants: 232 observed, 289.16 expected, observed/expected ratio (o/e) 0.8, 90% interval 0.72 to 0.89. Synonymous variants: 132 observed, 121.24 expected, observed/expected ratio (o/e) 1.09, 90% interval 0.94 to 1.26.
Homologues: Orthologues: chimpanzee RASL11B (99% identical), dog RASL11B (96% identical), macaque RASL11B (96% identical), pig RASL11B (95% identical), mouse Rasl11b (94% identical), rat Rasl11b (92% identical), guinea pig RASL11B (81% identical), tropical clawed frog rasl11b (75% identical), zebrafish rasl11b (65% identical). Paralogues in human: RASL11A (50% identical), RERG (28% identical), RERGL (27% identical), RASL12 (25% identical), RRAD (25% identical), REM2 (24% identical), REM1 (24% identical), GEM (23% identical), RRAS2 (23% identical), HRAS (23% identical), ERAS (22% identical), KRAS (22% identical), and 23 more.
Diseases named in the same sentence as RASL11B in open-access papers:
RASL11B is named in the same sentence as 13 diseases in open-access papers, as found by Europe PMC text mining. Sharing a sentence is not in itself a finding about the gene and the disease. The quoted sentences say what the papers report.
atherosclerosis (2 papers, 2024 to 2025). A disease characterized by the build-up of fatty material and calcium deposition in the arterial wall resulting in partial or complete occlusion of the arterial lumen. "MiR-181a and miR-144 regulate RASL11B, which participates in myocardial infarction, atherosclerosis, cardiac enlargement (ventricular hypertrophy), and heart failure through TGF-β1-mediated pathways." (PMID 40658689, 2025).
breast carcinoma (1 paper, 2020). "It has been confirmed by studies that NRIP3 and RASL11B play a role in suppressing cancer proliferation in breast cancer and renal cell carcinoma 31,32." (PMID 32626531, 2020).
clear cell renal cell carcinoma (1 paper, 2021). "Upregulated RASL11B inhibits cell proliferation, invasion, and migration, induces G0/G1 cell cycle arrest and promotes cell apoptosis in clear cell renal cell carcinoma (CCRCC)." (PMID 34059019, 2021).
glioma (1 paper, 2023). A benign or malignant brain and spinal cord tumor that arises from glial cells (astrocytes, oligodendrocytes, ependymal cells). "However, the expression and prognosis of KIT, CHIC2, EXOC1, IGFBP7, RASL11B or USP46 in glioma are unclear." (PMID 36043552, 2023).
melanoma (1 paper, 2025). A malignant, usually aggressive tumor composed of atypical, neoplastic melanocytes. "DANCR is a melanoma-associated lncRNA and conserved small non-coding RNA host gene that is expressed from equivalent regions in diverse vertebrate genomes and in a similar direction relative to the neighbouring USP46 and RASL11B protein coding genes." (PMID 41336739, 2025).
cancer (5 papers, 2011 to 2023). A tumor composed of atypical neoplastic, often pleomorphic cells that invade other tissues. "Finally, CDK2, LST1, NKD2 and RASL11B have also been implicated in a variety of cancer types." (PMID 22087225, 2011). "Impact of Rasl11b on overall proliferation is scientifically well supported, and the evidence from studies on zebrafish and human cancer cells is consistent." (PMID 35295214, 2022). "However, evidence that RASL12 functions as a small GTP-binding protein is lacking; In fact, studies have reported that RASL12 could be homologous to the RAS-like GTPases RERG, RASL11A, RASL11B, RASL10A and RASL10B, which play tumor-suppressive roles in human cancers." (PMID 34819106, 2021).
tumor (4 papers, 2008 to 2025). "To test this hypothesis we created two constitutively active Rasl11b molecules by introducing activating mutations based on the tumor-derived RAS mutations G12V and Q61L, thereafter both named Rasl11b* because of their similar influence." (PMID 18197245, 2008). "However, Rasl11b, a member of a putative tumor suppressor subgroup and only potent when Oep function is compromised, may represent an undescribed link between Cripto1 and the oncogenic process." (PMID 18197245, 2008).
RASL11B also shares sentences with these, for which no sentence is quoted: glaucoma (1 paper); heart failure (1); hepatocellular carcinoma (1); myocardial infarction (1); renal cell carcinoma (1); Ventricular hypertrophy (1).